EFNA1 (ephrin A1)
Diseases named in the same sentence as EFNA1 in open-access papers (continued):
Sharing a sentence is not in itself a finding about the gene and the disease.
multiple sclerosis (1 paper, 2015). A progressive autoimmune disorder affecting the central nervous system resulting in demyelination. "In support of the relevance and potential effect of such a strategy, ephrin-A1 and several EphA receptors were found to be upregulated in active lesions of multiple sclerosis patients." (PMID 26354550, 2015).
Ovarian cyst (1 paper, 2006). The presence of one or more cysts of the ovary. "Hence EphA1, EphA2, EphB2, EphB3, EphB6, ephrin A1, ephrin A5 and ephrin B1 were selected for further analysis in an additional fourteen tumor samples, one ovarian cyst and one ovarian adenoma." (PMID 16737551, 2006).
Pleural effusion (1 paper, 2025). The presence of an excessive amount of fluid in the pleural cavity. "Reclustering and cytoTRACE-based assessments of pleural effusion-derived metastases again revealed a positive correlation between the expression of EFNA1 and SCNN1A and the differentiation potential." (PMID 40787466, 2025).
proliferative diabetic retinopathy (1 paper, 2025). Advanced retinopathy due to diabetes mellitus characterized by the formation of new vessels in the retina. "In addition, serum Ephrin-A1 in proliferative diabetic retinopathy patients was higher than that in non-proliferative diabetic retinopathy patients, and CTRP9 level was lower than that in non-proliferative diabetic retinopathy patients." (PMID 39974734, 2025).
prostate tumor (1 paper, 2023). "In the earliest studies, it was shown how EphA2 activation without degradation by the means of low concentrations of ephrin-A1-Fc was a key way of efficiently inhibiting prostate tumor growth, at least in vitro." (PMID 37895923, 2023).
rectal adenoma (1 paper, 2012). "Copy number and mRNA expression of EFNA1 increased from rectal adenoma to carcinoma." (PMID 23158542, 2012).
rectal tumor (1 paper, 2025). "Patients with the G/G genotype for the EFNA1 (rs12904) variant showed an association with TNM stages and rectal tumor location (OR > 2.0, p = 0.001)." (PMID 40004552, 2025).
renal cell carcinoma (1 paper, 2022). "EFNA1 plays a pivotal role in the pathogenesis of several tumors, including renal cell carcinoma, bladder, and prostate cancer." (PMID 36352089, 2022).
stomach adenocarcinoma (1 paper, 2022). "In a study of 222 patients with gastric adenocarcinoma that underwent gastrectomy, immunohistochemical analysis of the samples showed that EFNA1 expression suggested a poor disease-specific survival benefit." (PMID 35309935, 2022).
tumor (97 papers, 2005 to 2025). "By integrating ChIP-Seq and RNA-Seq data, we identified numerous aberrant SEs and SE-associated genes, among which EFNA1 is spotlighted as a novel tumor-specific SE target in CC." (PMID 39964764, 2025). "Its expression increases with tumor grade and predicts poor prognosis, while higher levels of ephrin-A1 are associated with lower-grade tumors." (PMID 41200151, 2025). "EphA2 and ephrin-A1 are expressed in tumours and associated vessels, with mouse models indicating that EphA2 expression in vessels is important for efficient angiogenesis." (PMID 37760615, 2023). "Lastly, while ephrin-A1 expression was found to be increased in cancer tissues, its low staining was linked to more aggressive tumor features." (PMID 34445116, 2021). "Though we demonstrate increased macrophages in ephrin-A1-deficient lungs, it remains to be seen if these macrophages are polarized towards an anti-tumor or a pro-tumor response." (PMID 32399207, 2020). "We initially investigated the impact of ephrin-A1 host deficiency on primary tumor growth by implanting 4T1 cells in a mixture of PBS and Matrigel orthotopically into the mammary fat pads of syngeneic BALB/c femaleEfna1+/+ andEfna1-/- mice." (PMID 32399207, 2020). "The revealed genes EFNA1 and TFRC encode ephrin A1 and the transferrin receptor, which play an important role in tumor development through inducing tumor angiogenesis and iron uptake, respectively." (PMID 31523389, 2019). "Interaction between EphA2 and Ephrin A1, along with other guidance molecules, will navigate developmental guidance that causes sheets of cell layers to become tumours." (PMID 30914876, 2018). "Other members of the Eph receptor and ephrin families, including EphA2, EphB4, ephrin A1, and ephrin A3, have previously been implicated in radioresistance in different tumor models." (PMID 25879388, 2015). "The EFNA1 protein level was significantly linked to tumor stage, whereupon patients with advanced tumor stage frequently showed a low EFNA1 protein expression." (PMID 25025847, 2014). "In terms of molecular mechanism, our signature implicated Ephrin-A1 as a novel downstream mediator contributing to TGF-β-driven tumor suppression." (PMID 24890385, 2014). "A positive EPHA1 and EPHA2 protein staining as well as a low EFNA1 protein level were significantly linked to more aggressive tumor features, but only a positive EPHA1 immunoreactivity was significantly associated with poor survival." (PMID 25025847, 2014). "In head and neck cancers, increased ephrin-A1 expression was associated with pO2 in tumor microenvironment." (PMID 24040255, 2013). "The aim of our study was to investigate the underlying mechanisms of tumor suppressor effect of ephrin-A1 in NSCLC." (PMID 22824143, 2012). "Although EphA2 is implicated in tumor growth and metastasis of many types of solid cancers through ligand-independent signaling, it can also suppress cell growth via ligand-dependent signaling through ephrin-A1, its primary binding partner." (PMID 40867322, 2025). "The current study investigated the mechanisms underlying ephrin-A1 modulation of angiogenesis through examining the effect of hypoxia on ephrin-A1 expression and secretion in tumor cells and the possible association of ephrin-A1 with eNOS/NO in tumor angiogenesis." (PMID 24040255, 2013). "Based on our findings that S100A4 is associated with small tumor size and a less aggressive phenotype, one might speculate that S100A4-mediated induction of ephrin-A1 could be implicated in reduced tumor growth and invasiveness in NSCLC." (PMID 22853000, 2012). "Furthermore, the correlation between EFNA1 SNP genotyping and tumor characteristics showed that polymorphisms in the EFNA1 gene may influence the likelihood of tumorigenesis and the risk of disease progression." (PMID 38651144, 2024). "Thus, ephrin A1-associated tumor suppression might result from EphA2 downregulation as well as direct signaling through EphA2." (PMID 32811512, 2020).
tumor (continued). "EFNA1, CXCL8, and PPP1R14A emerged as prognostic biomarkers for CESC, showing significant associations with survival, tumor stage, and immune infiltration." (PMID 40406253, 2025). "This divergence is evident in our study, in which EFNA2 and EFNA5 overexpression reduced cell proliferation, migration, and tumor growth, in contrast to EFNA1’s tumor-promoting effects." (PMID 39964764, 2025). "The high-CMLHMS group exhibited upregulation of genes such as TRPC4AP, NUSAP1, EFNA1, KMT2A, and NCOA6, which are implicated in chromatin remodeling, cell proliferation, and tumor progression." (PMID 40144021, 2025). "Remarkably, EFNA1 knockdown led to significant inhibition of tumor growth, as evidenced by reductions in both tumor volume and weight in comparison with the control group." (PMID 39964764, 2025). "Together, these observations strongly suggest that EFNA1 drives tumor progression primarily through activation of the Src/AKT/STAT3 signaling axis." (PMID 39964764, 2025). "These in vitro and in vivo data strongly suggest that EFNA1 is essential for the proliferation, migration, and tumor growth of CC cells." (PMID 39964764, 2025). "EFNA1, a cell surface ligand, primarily interacts with the EphA2 receptor to regulate tumor cell migration, invasion, and proliferation, and its overexpression is closely associated with tumor progression in numerous cancers." (PMID 40787466, 2025). "Tumor cells exhibited significant enrichment of exosome-associated genes, most notably SCNN1A and EFNA1, which were significantly upregulated in metastatic lesions and correlated with a poorer prognosis." (PMID 40787466, 2025). "EFNA1, a ligand of EphA2 receptor tyrosine kinase, is overexpressed in AFP‐producing HCC and can induce the expression of genes associated with tumor cell growth, angiogenesis, invasion, and metastasis, leading to poor prognosis in HCC patients with AFP." (PMID 39041652, 2024). "For instance, EPHA2 expression on extracellular vesicles can influence nearby ephrin-A1-expressing tumor cells." (PMID 38612645, 2024). "EFNA1 widely participates in tumorigenesis by influencing tumor angiogenesis, malignant cell events and invasiveness." (PMID 38528036, 2024). "The small molecule targeting to EFNA1 was identified by molecular docking and the anti-tumor effects were verified by in vitro and in vivo models with radiation treatment." (PMID 37160815, 2023). "Several lines of studies have examined the molecules targeting to EFNA1 and evaluated the anti-tumor effects." (PMID 37160815, 2023). "EFNA1 is a member of ephrin family which has been reported to be involved in multiple malignant progresses like tumor growth, invasiveness and metastasis." (PMID 37160815, 2023). "To determine the putative contribution of ADAM17 to the release of endogenous ephrin-A1 from the cell surface of tumor cells, we analyzed the supernatant of ADAM17 inhibited cells (TMI-005 or MEDI3622 treated) and compared it to their untreated controls." (PMID 36998455, 2023). "EFNA1 has been reported to be upregulated in a variety of malignancies and critical for tumor progression." (PMID 37160815, 2023). "Results showed that knockdown of EFNA1 significantly suppressed tumor growth on both size and weight, therefore certifying that EFNA1 was critical for ESCC proliferation and migration." (PMID 37160815, 2023). "To determine the underlying mechanism of EFNA1 in promoting tumor growth, we analyzed the DEGs between ESCA samples with high and low expression level of EFNA1 from TCGA dataset." (PMID 37160815, 2023). "The differential gene expression levels between the tumor and adjacent tissues displayed in the box plot show that the EFNA1 expression level was significantly (p < 0.001) higher in the tumor tissue than in the normal ones." (PMID 38137332, 2023). "uPAR expression, in fact, is increased in EC with Marimastat as well as Ephrin A1 expression, that it is known to promote RhoA activation and amoeboid transition in tumor cells." (PMID 36759828, 2023).
tumor (continued). "As the tumour stage progressed, the expression of EFNA1 increased, while that of TNFAIP8 and TNFAIP8L3 decreased." (PMID 34344926, 2021). "It was also reported that soluble monomeric ephrin-A1 showed proliferative activity in some cultured tumor cells such as HeLa and SK-Br-3 cells." (PMID 33804570, 2021). "EPHA2 and ephrin-A1 overexpression, along with elevated MVD, was associated with the tumor TNM stage and the presence of perineural and perivascular invasion." (PMID 34445116, 2021). "For more than 30 years after researchers find this gene, a ton of proof upheld that EFNA1 assumes a basic part in tumor development (eg., Angiogenesis and progression)." (PMID 34079823, 2021). "The ADAM12-mediated cleavage of ephrin-A1 induces vascular leakage in the lungs, resulting in an enhancement of tumor cell intravasation defined as metastasis." (PMID 33804570, 2021). "In a comparison of 6872 tumors and 691 control tissues, EFNA1 gene was found to overexpress in most tumor tissues, especially in ESCA." (PMID 34399788, 2021). "The results suggest that tumor-derived ephrin-A1 is not only a potential biomarker to predict lung metastasis from the primary tumor highly expressing ephrin-A1 but also a therapeutic target of lung metastasis." (PMID 33804570, 2021). "Tumor-derived soluble ephrin-A1 levels were gradually increased in serum along with the growth of tumor mass." (PMID 33804570, 2021). "We previously reported that soluble forms of ephrin-A1 were increased in the serum of tumor-bearing mice." (PMID 33804570, 2021). "The results showed that EFNA1 knockdown significantly inhibited the proliferation of tumor cells (P < 0.05)." (PMID 34399788, 2021). "We established that both tumor-derived soluble ephrin-A1 and tissue-derived soluble ephrin-A1 were gradually increased in serum concomitant with tumor growth." (PMID 33804570, 2021). "Based on the previous results, it is concluded that the abnormal expression level of ephrin-A1 play a critical role in the tumor occurrence, development and metastasis." (PMID 34079823, 2021). "We found elevated levels of tumor-derived ephrin-A1 in the serum and the urine in the tumor-bearing mice." (PMID 33804570, 2021). "Multiple studies in tumor cells of different origin have shown that EFNA1 treatment leads to increased tyrosine phosphorylation of EphA2, e.g., at Y588 with a concomitant decrease in phosphorylation of EphA2 at S897." (PMID 33671073, 2021). "EFNA1 inhibits the proliferation of tumor cells in NSCLC by increasing the expression of tumor suppressor gene cdx-2." (PMID 34399788, 2021). "Literature have documented that EFNA1 extensively involved in tumorigenesis by influencing tumor angiogenesis, malignant cell events, and invasiveness." (PMID 34399788, 2021). "Subsequently, we checked if soluble forms of ephrin-A1 derived from the primary tumors (tumor-derived ephrin-A1) is released to urine." (PMID 33804570, 2021). "Expression of ephrin-A1 was found in the process of embryonic vascular development and tumor growth." (PMID 32758187, 2020). "Ephrin-A1, a cell surface protein involved in adhesion and migration, has been shown to be tumor suppressive in the context of the cancer cell." (PMID 32399207, 2020). "Ephrin A1 has been demonstrated to be present at low levels and to possess tumor suppressing properties dependent on cell-to-cell contact in a variety of tumors." (PMID 32811512, 2020). "Previous studies reported that ephrin-A1 has also been shown to be expressed in the developing vasculature during embryogenesis and in nenvascular cells during tumor growth." (PMID 32758187, 2020). "For PC2, top positively correlated genes included IFITM1 and GPX1, both have been reported to be associated with risk of numerous cancers, while most negatively PC2 correlated genes included common-known tumor over-expressed genes such as EFNA1." (PMID 32231683, 2020).
tumor (continued). "While decreased extravasation of tumor cells may explain in part the decreased lung metastases inEfna1-/- mice, another possibility is that once tumor cells have extravasated and established in the lung, they have reduced fitness of survival in ephrin-A1-deficient lungs, compared to wild-type lungs." (PMID 32399207, 2020). "(Flow cytometry files (fcs), gating and analysis (wsp), and panels (xlsx) containing immune profiling of 4T1-GFP-luciferase tumor-bearing lungs fromEfna1+/+,Efna1+/-, andEfna1-/- littermate mice (related toFigure 2D, 3C, D))." (PMID 32399207, 2020). "The oncogenic function of EPHA2 is ligand-independent, as exogenous ephrin-A1 stimulation inhibits tumor cell proliferation." (PMID 31160603, 2019). "The average tumor weight in the ephrin-A1-overexpressing group treated with LEF were significantly higher than that in empty vector-transfected TCCSUP group upon LEF treatment (p < 0.05)." (PMID 29367676, 2018). "In general, EphA2 works via Ephrin A1’s signaling axis to regulate multiple events in the transformation of tumour malignancies." (PMID 30914876, 2018). "Hypoxia-inducible transcription factor-2alpha in endothelial cells regulates tumor neovascularization through activation of ephrin A1." (PMID 28792525, 2017). "EPH-A2 and Ephrin-A1 mRNA expression was quantified by real-time PCR in 14 ERMS tumour samples and in normal skeletal muscle (NSM)." (PMID 28985758, 2017). "While ligand-dependent EphA2-activation has been considered tumor suppressive, recent reports have highlighted a role for EphA2-ephrin-A1 signaling in tumor cell plasticity and a shift from mesenchymal to amoeboid morphology and increased single cell invasion." (PMID 27246245, 2016). "Ephrin-A1 ligation of EphA2 and subsequent receptor activation has been proposed to be tumor suppressive, although other studies point to an important role for kinase dependent EphA2 activity in cancer development." (PMID 27246245, 2016). "In ERMS, high expression of PAX7 upregulates EPHA3 and EFNA1 to promote migration and invasiveness of tumor cells." (PMID 26636678, 2015). "To demonstrate a functional role for Ephrin-A1 in tumor suppression, we used shRNA knockdown in M3 cells and showed that ephrin-A1 knockdown significantly increased primary tumorigenesis." (PMID 24890385, 2014). "Contrary, in the present study, ccRCC patients with a high EFNA1 protein expression had frequently a lower tumor stage (p = 0.004)." (PMID 25025847, 2014). "Tumor cells exhibited cytoplasmic and nuclear staining for EFNA1 which was observed in all positive cells." (PMID 25025847, 2014). "An abnormal expression of EPHA1, EPHA2 and EFNA1 with influence on patient outcome has been demonstrated in different tumor entities." (PMID 25025847, 2014). "Compared to the primary tumor, the EFNA1 expression was lower in metastases to the lymph nodes, adrenal gland, and bone." (PMID 25025847, 2014). "Activation by interaction with ephrin-A1 causes phosphorylation of EphA2 that generates an anti-oncogenic signal as shown by the observation that forced activation by exposure to soluble ephrin-A1 can inhibit tumor growth both in vitro and in vivo." (PMID 25344320, 2014). "Being a ligand for several of the Eph family receptor tyrosine kinases, the cell surface protein ephrin-A1 is involved in multiple biological processes including metastasis and tumor angiogenesis." (PMID 24215488, 2013). "Although ephrin-A1 plays a critical role in tumor angiogenesis and seems to be involved in response to hypoxia, most of previous studies have mainly focused on ephrin-A1 as a membrane-bound protein." (PMID 24040255, 2013). "Hypoxia, ephrin-A1 and endothelial nitric oxide synthase (eNOS) have been proved to play critical roles in tumor angiogenesis." (PMID 24040255, 2013). "The immunohistohemical staining pattern and distribution of OPN, S100A4 and ephrin-A1 in the tumor tissues have been described previously." (PMID 24215488, 2013).